RET (ret proto-oncogene)
Diseases named in the same sentence as RET in open-access papers (continued):
Sharing a sentence is not in itself a finding about the gene and the disease.
multiple endocrine neoplasia type 2 (continued). "Some data indicates that RET c.2372A > T is associated with familial medullary thyroid carcinoma (FMTC), hereditary cancer-predisposing syndrome, Hirschsprung disease, multiple endocrine neoplasia (MEN) including types 1, 2a, 2b, and 4, pheochromocytoma, and renal adysplasia." (PMID 29504908, 2018). "A germ-line activating mutation in the RET (REarranged during Transfection) protooncogene is reported in nearly all cases of hereditary forms of MTC associated with multiple endocrine neoplasia type 2 (MEN 2), and a somatic RET mutation can be present in up to 50% of sporadic forms of MTC." (PMID 28018431, 2016). "The kinase signalling subgroup, includes characteristic mutations in REarranged during Transfection (RET) in Multiple Endocrine Neoplasia type 2 (MEN2), Neurofibromatosis type 1 (NF1), transmembrane protein 127 (TMEM127), MYC associated factor X (MAX), EGLN1 (PHD2), KIF1 and IDH1." (PMID 27535829, 2016). "In particular, germ-line mutations in the RET gene are responsible for the hereditary tumour syndrome (i.e., multiple endocrine neoplasia type 2, MEN 2) which includes three subgroups, MEN 2A, MEN 2B, and familial medullary thyroid carcinoma (FMTC), depending on the tissue involved." (PMID 23133451, 2012). "Although reported gene variants in the RET oncogene have been directly associated with multiple endocrine neoplasia type 2 and hereditary medullary thyroid carcinoma, other mutations are classified as variants of uncertain significance (VUS) until the associated clinical phenotype is made clear." (PMID 21479187, 2011). "Paediatric MTCs are nearly always associated with multiple endocrine neoplasia type 2 (MEN2), caused by germline RET P/LPV." (PMID 40361475, 2025). "Multiple endocrine neoplasia type 2 (MEN2) is an autosomal-dominant inherited syndrome caused by an activating germline mutation of the RET proto-oncogene (MIM *164761) located on chromosome 10." (PMID 38339246, 2024). "Multiple endocrine neoplasia type 2 (MEN2) is a hereditary cancer syndrome caused by germline-activating pathogenic variants in the RET proto-oncogene." (PMID 39231479, 2024). "Multiple endocrine neoplasia type 2 (MEN2) is an inherited cancer syndrome associated with germline variations of the RET proto-oncogene, which encodes a tyrosine kinase receptor whose activation promotes cell growth, proliferation, and differentiation." (PMID 37239385, 2023). "An autosomal-dominant hereditary syndrome called multiple endocrine neoplasia type 2 (MEN2) is caused by activating pathogenic variants (PVs) in the rearranged during transfection gene (RET) on chromosome 10q11.2." (PMID 35888179, 2022). "Approximately 89% of patients with bPHEOs develop multiple endocrine neoplasia type 2 (MEN2) caused by germline mutation of the RET (rearranged during transfection) proto-oncogene and von Hippel–Lindau (VHL) disease caused by the VHL gene." (PMID 36704524, 2022). "Activation mutations in the proto-oncogene RET lead to the development of an autosomal dominant syndrome called multiple endocrine neoplasia type 2 (MEN2)." (PMID 33391357, 2020). "Activating mutations in the RET proto-oncogene lead to multiple endocrine neoplasia type 2 (MEN2), characterized by the development of medullary thyroid carcinoma, often associated with PCCs and hyperparathyroidism." (PMID 28471419, 2017). "Multiple endocrine neoplasia type 2 (MEN-2) is an autosomal dominant syndrome caused by germline activating mutations of the RET proto-oncogene and has been categorized into three distinct clinical forms." (PMID 23455356, 2013). "Although most cases are sporadic, CLA has been associated with multiple endocrine neoplasia type 2A (MEN2A), a hereditary syndrome caused by germline alterations in the RET proto-oncogene." (PMID 42194535, 2026).
multiple endocrine neoplasia type 2 (continued). "Variants in the human receptor tyrosine kinase RET can cause RET loss-of-function and Hirschsprung's disease (HSCR), while activating RET variants drive cancers including multiple endocrine neoplasia type 2 (MEN2)." (PMID 41816802, 2026). "Mucosal neuromas are benign proliferations of peripheral nerves that most commonly occur as part of multiple endocrine neoplasia type 2B (MEN2B), a hereditary syndrome associated with germline mutations of the RET proto-oncogene." (PMID 42022710, 2026). "In multiple endocrine neoplasia type 2A (MEN2A), which also demonstrates autosomaldominant inheritance, pathogenic variants are present in the RET gene." (PMID 40893023, 2025). "RET rearrangements are often associated with childhood radiation exposure, while germline RET mutations are a hallmark of medullary TC (MTC) and familial syndromes like Multiple Endocrine Neoplasia type 2 (MEN2)." (PMID 40507281, 2025). "MEN2 encompasses three subtypes: type 2A (MEN2A), type 2B (MEN2B), and familial medullary thyroid carcinoma (FMTC), each associated with specific clinical features and germline RET mutations." (PMID 40283452, 2025). "Alternatively, RET-p.S891A associated with OSMR gene (p.G513D) variant has been identified in lichen amyloidosis and familial medullary thyroid carcinoma." (PMID 39585007, 2024). "Multiple endocrine neoplasia type 2 (MEN2, previously MEN2A) is due to activating missense mutations in the RET proto-oncogene, located on chromosome 10q11.21." (PMID 38038882, 2024). "Multiple endocrine neoplasia type 2 (MEN2) is an autosomal-dominant inherited orphan disease, caused by activating germline mutations of the RET gene." (PMID 38339246, 2024). "While roughly 75% cases are sporadic, 25% are hereditary and are a part of multiple endocrine neoplasia type 2 (MEN2), which is caused by REarranged during Transfection (RET) germline mutations." (PMID 37835559, 2023). "In germline RET mutation, MTC is classified under three different phenotypes: familial MTC, and multiple endocrine neoplasia types 2A and 2B (MEN2)." (PMID 36009450, 2022). "Approximately 25% of MTCs occur in a hereditary form as multiple endocrine neoplasia type 2 A (MEN2A), MEN2B or familial MTC (FMTC, a variant of MEN2A), virtually all of which are caused by germline mutations in the RET proto-oncogene." (PMID 36344509, 2022). "Germline mutations of RET gene are responsible for the cases of autosomal dominant hereditary multiple endocrine neoplasia type 2 (MEN2A and MEN2B), as well as familial medullary thyroid carcinoma." (PMID 36358717, 2022). "Germline loss-of-function variants in RET cause Hirschsprung’s disease (HSCR), a congenital intestinal malformation, while activating variants cause multiple endocrine neoplasia type 2 (MEN 2), an autosomal dominantly inherited cancer-susceptibility syndrome." (PMID 34925234, 2021). "Mutations in the RET (Rearranged during transfection) proto-oncogene account for most MTC cases and can occur sporadically or as inherited germline events in the multiple endocrine neoplasia type 2A (MEN2A) and 2B (MEN2B) syndromes." (PMID 32231639, 2020). "Multiple endocrine neoplasia type 2 (MEN2) affects patients with RET proto-oncogene mutations." (PMID 29396759, 2018). "MTC originates as a sporadic (75–80%) malignancy or a manifestation of hereditary syndromes (20–25%), i.e., multiple endocrine neoplasia type 2 (MEN2A or MEN2B)/familial MTC, with an autosomal dominant pattern due to germline mutations of the RET gene." (PMID 28929017, 2017). "Germline mutations of the RET gene are responsible for two different genetic disorders, Hirschsprung's disease (HSCR) and Multiple Endocrine Neoplasia type 2 (MEN2), due to loss-of-function and gain-of-function mutations, respectively." (PMID 27034161, 2016). "Mucosal neuromas are highly associated with multiple endocrine neoplasia type 2b (MEN-2b), which occurs in patients with germline mutation of RET genes." (PMID 26444007, 2015).
multiple endocrine neoplasia type 2 (continued). "Rearranged during transfection (RET) is a tyrosine kinase receptor proto-oncogene, point mutation of which underlies Multiple Endocrine Neoplasia Types 2A and 2B (MEN2A/MEN2B) and familial medullary thyroid cancer." (PMID 26793165, 2015). "Other RET mutations cause MEN 2A syndrome, familial medullary thyroid carcinoma, or Hirschsprung's disease." (PMID 22429913, 2012). "Activating germ-line point mutations in the RET receptor are responsible for multiple endocrine neoplasia type 2-associated MTC, whereas somatic RET rearrangements are prevalent in PTC." (PMID 17997826, 2007). "For example, in genetic testing for multiple endocrine neoplasia type 2 (MEN2), it refers to the risks and benefits resulting from genetic test use, in which RET mutation testing provides a means to identify individuals who would benefit from preventive surgery." (PMID 40869806, 2025). "For patients with a RET oncogene mutation, it is advisable to screen for hyperparathyroidism and pheochromocytoma to rule out multiple endocrine neoplasia type 2 (MEN-2) syndrome." (PMID 40698208, 2025). "In the other 25% of patients, MTC is hereditary, mainly in the context of multiple endocrine neoplasia type 2A (MEN2A) (90–95%) and type 2B (MEN2B) (5–10%), which are autosomal dominant syndromes caused by a germline mutation in the REarranged during Transfection (RET) proto-oncogene." (PMID 39272838, 2024). "Additionally, at least some of these RET affected individuals had a known diagnosis of Multiple Endocrine Neoplasia type 2 (MEN2) prior to pregnancy." (PMID 36637675, 2023). "Notably, RET rearrangements occur in multiple endocrine neoplasia type 2A/B and familial medullary thyroid carcinoma, emphasising the therapeutic importance of targeting this kinase receptor." (PMID 35798698, 2022). "MTC is sporadic in origin in 60 to 75 % of all patients with MTC, while the others exhibit germline mutations in the RET proto-oncogene, namely patients with multiple endocrine neoplasia type 2A (MEN2A), multiple endocrine neoplasia type 2B (MEN2B), and familial MTC syndrome (FMTC)." (PMID 27461534, 2016). "One patient, OS-250, carried a germline RET mutation, which at the time of diagnosis had not yet manifested by multiple endocrine neoplasia type 2 but the mutation co-segregated with breast cancer and rhabdomyosarcoma in two first-degree relatives." (PMID 26632267, 2015). "MTC, which accounts for 5-8% of all thyroid cancers, is mainly sporadic in nature, while a hereditary pattern (multiple endocrine neoplasia type 2 (MEN 2), transmitted as an autosomal-dominant trait due to germline mutations of the RET proto-oncogene, accounts for about 29% of cases." (PMID 23514614, 2013). "Regarding the etiology of multiple endocrine neoplasia type 2 (MEN2) syndrome, the responsible genetic mutation is represented by the activating mutation of the receptor tyrosine kinase, also known as the rearranged during transfection (RET) protein, which is located on chromosome 10q." (PMID 39201946, 2024). "Multiple endocrine neoplasia type 2A (MEN2A) or Sipple Syndrome is an autosomal dominant syndrome, first described by Sipple and later characterized in multiple kindreds by Schimke, caused by misense mutations in the RET protooncogene, a tyrosine kinase receptor." (PMID 21843357, 2011). "Constitutively active RET mutants give rise to the inherited cancer syndrome multiple endocrine neoplasia type 2 (MEN2), which is characterized by the adrenal tumor pheochromocytoma (PCC), while activating mutations or increased RET expression are found in a subset of sporadic PCC." (PMID 38687678, 2024).
multiple endocrine neoplasia type 2 (continued). "This cohort study refers to patients who were diagnosed with familial medullary thyroid carcinoma (MTC) and underwent RET genetic testing in Cyprus between years 2002 and 2017." (PMID 29396759, 2018). "Missense, germline gain-of-function mutations in the RET proto-oncogene are associated with type 2 multiple endocrine neoplasia syndromes (MEN2A or MEN2B) and familial medullary thyroid carcinoma (FMTC)." (PMID 28647780, 2017). "Constitutively active mutations in RET cause the hereditary cancer syndromes multiple endocrine neoplasia type 2 (MEN2A and MEN2B) and familial medullary thyroid carcinoma." (PMID 23639815, 2013). "Single nucleotide substitutions in RET genes are responsible for a range of autosomal dominant syndromes, including Pfeiffer syndrome, Crouzon syndrome, Apert syndrome, achondroplasia, thanatophoric dysplasia, and multiple endocrine neoplasia types 2A and 2B (MEN2A and MEN2B)." (PMID 39969160, 2025). "There are no reports on the relationship between familial medullary thyroid carcinoma (FMTC) associated with cutaneous amyloidosis (CA) and RET or OSMR/IL31RA gene mutations." (PMID 26356818, 2015). "Multiple endocrine neoplasia type 2 (MEN2) is composed of three clinical subtypes, multiple endocrine neoplasia type 2A (MEN2A), familial medullary thyroid carcinoma, and multiple endocrine neoplasia type 2B, all of which are associated with germline mutations in the RET proto-oncogene." (PMID 23236420, 2012). "Disruption of function by germline mutations in RET have been associated with several diseases in humans including three related inherited cancers: multiple endocrine neoplasia type IIA (MEN2A), multiple endocrine neoplasia type IIB (MEN2B), and familial medullary thyroid carcinoma (FMTC)." (PMID 21479187, 2011). "The child (patient IV.5) had two RET-negative siblings (IV.6 and IV.7), while their mother was the index-case (III.6) of a family confirmed with multiple endocrine neoplasia type 2." (PMID 39585007, 2024).
pheochromocytoma (191 papers, 1996 to 2026). "Among patients who underwent genetic testing to assess the presence of germline mutations predisposing to pheochromocytoma, 33.3% were found to have genetic defects, most commonly in the RET gene (n = 6)." (PMID 38655872, 2025). "The phenotypic penetrance and age of onset of pheochromocytomas correlate strongly with specific RET codon mutations." (PMID 40649858, 2025). "Although traditionally considered rare, advances in genetic screening have revealed that up to 35% of pheochromocytomas are associated with germline mutations in known susceptibility genes, including RET, VHL, NF1, and SDHx subunits, among others." (PMID 41465145, 2025). "This study demonstrated that patients with pheochromocytoma and concomitant RET pathogenic variant are at greater risk of developing extra-adrenal forms of the disease." (PMID 38849646, 2024). "The aggressiveness of MTC in patients with MEN2 correlates with the pheochromocytoma penetrance and the severity of the autosomal dominant (AD) pathogenic RET proto-oncogene variants." (PMID 38637882, 2024). "MEN2A is characterized by the presence of MTC associated with pheochromocytoma hyperparathyroidism or both, with a different frequency depending on the specific RET mutation." (PMID 39839784, 2024). "Among the germline RET mutation-positive patients, seven patients had cutaneous lichen amyloidosis, six each had pheochromocytoma, cutaneous lichen amyloidosis, and hyperparathyroidism." (PMID 38260132, 2023). "This patient had paroxysmal hypertension, consistent with the clinical manifestation of pheochromocytoma caused by mutations in the RET proto-oncogene gene." (PMID 37335636, 2023). "A literature analysis found that pheochromocytoma is a tumor with high genetic heterogeneity, and the RET proto-oncogene is a common pathogenic gene for bilateral adrenal pheochromocytoma." (PMID 37335636, 2023). "Patients with RET mutations often have gland tumors other than pheochromocytoma, forming the MEN2 type." (PMID 37335636, 2023). "Most patients with pheochromocytoma with RET mutations exhibit paroxysmal elevated or normal blood pressure, indicating a paroxysmal release of catecholamines in these patients, causing a paroxysmal increase in blood pressure." (PMID 37335636, 2023). "AMH can be sporadic or familial, resulting from germline mutations of genes known to cause pheochromocytoma, such as the RET gene in multiple endocrine neoplasia type 2 (MEN2) syndrome, or in the NF1, SDHB, and MAX genes." (PMID 36896586, 2023). "Pheochromocytomas are a group of tumors with high genetic heterogeneity, and the clinical characteristics of rearranged during transfection (RET)-mutated pheochromocytoma with medullary spongiform kidney are rarely studied." (PMID 37335636, 2023). "MEN2A and MEN2B patients are also at increased risk for pheochromocytomas and should begin screening at 11–16 years old depending on risk profile, determined by the specific RET mutation." (PMID 36291833, 2022). "A phase II study involving the use of sunitinib in the treatment of advanced/metastatic paraganglioma and pheochromocytoma found one patient with MEN2A and a germline RET variant experienced a 64% tumor volume reduction." (PMID 35685436, 2022). "RET polymorphic alleles were reported as an additive effect on the estimated risk of age-related pheochromocytoma penetrance in MEN2 patients." (PMID 33777662, 2021). "For example, when PPGL-predisposing RET C634R mutation was introduced to PC12 rat pheochromocytoma cells, the cells underwent neuronal differentiation rather than proliferation." (PMID 33947839, 2021). "MEN2A is characterized by MTC, pheochromocytoma, and primary hyperparathyroidism (pHPT), and is sometimes associated with either cutaneous lichen amyloidosis in patients with RET codon 634 mutation or Hirschsprung’s disease." (PMID 34944814, 2021).